LINC01456 (long independently transcribed non-coding RNA 1456)
Gene: Long non-coding RNA gene on chromosome X (17,884,619 to 18,104,791, reverse strand). Ensembl gene ENSG00000225882.
Diseases named in the same sentence as LINC01456 in open-access papers:
LINC01456 is named in the same sentence as 3 diseases in open-access papers, as found by Europe PMC text mining. Sharing a sentence is not in itself a finding about the gene and the disease. The quoted sentences say what the papers report.
ovarian carcinoma (1 paper, 2019). A malignant neoplasm originating from the surface ovarian epithelium. "According to reports, LINC01456 is a risk factor in ovarian cancer and is involved in the progression of ovarian cancer." (PMID 31850229, 2019).
LINC01456 also shares sentences with these, for which no sentence is quoted: breast carcinoma (1 paper); cancer (1).